HOXB7 (homeobox B7)
Diseases named in the same sentence as HOXB7 in open-access papers (continued):
Sharing a sentence is not in itself a finding about the gene and the disease.
intrahepatic cholangiocarcinoma (4 papers, 2019 to 2025). A carcinoma that arises from the intrahepatic bile duct epithelium in any site of the intrahepatic biliary tree. "However, the specific mechanism by which HOXB7 promotes the malignant progression of intrahepatic cholangiocarcinoma (ICC) remains unclear." (PMID 30664713, 2019).
liver cancer (4 papers, 2017 to 2025). An epithelial or non-epithelial malignant neoplasm that arises from the liver. "HOXB7 has been shown to enhance the proliferation and metastasis of liver cancer cells by activating the MAPK/ERK pathway." (PMID 41040515, 2025). "High HOXB7 expression was significantly correlated with several clinicopathologic parameters, including multiple tumors (P=0.007), vascular invasion (P=0.010), satellite lesion (P=0.003), and Barcelona Clinic Liver Cancer (BCLC) Stage B+C (P=0.003)." (PMID 28454092, 2017).
breast tumors (3 papers, 2023 to 2025). "In this study, a non-toxic PEG-pGlu calcium phosphate nanocarrier for HOXB7 siRNA was evaluated both in vitro and in animal models bearing Luminal A breast tumors and showed promising capacity for gene delivery without presenting cytotoxicity." (PMID 39458966, 2024). "In the SQ breast tumors, we observed significantly upregulated mRNA levels of the Oct3/4 regulatory network, including ONSS, and several other PTFs, including Nanog, Sall4, Sox2, Sox4, FoxA2, Gata6, Zic2 and HoxB7, as well as Oct3/4 isoform B, polycomb suppressors Bmi1, EzH2, Amigo and Dkk1." (PMID 37298091, 2023).
colon cancer (3 papers, 2019 to 2022). "HOXB7 was found to simulate DNA damage repair and confer chemoresistance through interacting with Ku70, Ku80, DNA‐PKcs in colon cancer, which was involved in DSB repair." (PMID 31568655, 2020). "In colon cancer, HOXB7 stimulates DNA repair through interaction with KU70/80 upon etoposide treatment." (PMID 31568655, 2020).
head and neck squamous cell carcinoma (3 papers, 2019 to 2023). A squamous cell carcinoma that arises from any of the following anatomic sites: lip and oral cavity, nasal cavity, paranasal sinuses, pharynx, larynx, and salivary glands. "However, its expression pattern and oncogenic role of HOXB7 in head and neck squamous cell carcinoma (HNSCC) remain largely unexplored." (PMID 34303375, 2021). "Here, the same tendency in expression changes of TGM2, MMP2, CLDN7, HOXB7, and LCP1 can be found in different cancer types, including cervical and head and neck squamous cell carcinoma." (PMID 30918060, 2019).
hydronephrosis (3 papers, 2011 to 2015). Collection of urine in the renal pelvis that results in dilatation of the renal pelvis and calyces. "The development of a urinary concentrating defect reveals a crucial role for Dicer in the CD, in line with a previous study where Dicer inactivation in HoxB7 expressing cells leads to congenital hydronephrosis and development of multiple cysts in the CD." (PMID 25799508, 2015). "The third evidence supporting a role for Robo2 in the anti-reflux mechanism is the golf-hole like ureteral orifice dilatation detected by both micro-ultrasonography and Hoxb7-GFP reporter gene in Robo2 mutant mice with hydronephrosis." (PMID 21949750, 2011).
osteosarcoma (3 papers, 2021 to 2025). A usually aggressive malignant bone-forming mesenchymal neoplasm, predominantly affecting adolescents and young adults. "In osteosarcoma, HOXB7 silenced significantly inhibited proliferation and invasion of osteosarcoma cells." (PMID 34303375, 2021).
pancreatic adenocarcinoma (3 papers, 2013 to 2015). "HOXB7 is overexpressed in pancreatic adenocarcinomas and in the two studied pancreatic cell lines; the siRNA assay suggests that HOXB7 is involved in pancreatic cell proliferation and apoptosis." (PMID 24088503, 2013).
prostate carcinoma (3 papers, 2020 to 2024). A carcinoma that arises from epithelial cells of the prostate gland. "For example, lncRNA SNHG8 is reported to contribute to the development of prostate cancer by elevating HOXB7 expression via sponging miR-384." (PMID 34446088, 2021). "By contrast, GO analysis of the genes upregulated in the BPH-PCa group while downregulated in men with symptomatic BPH were several transcription factors related to prostate cancer, such as NKX3-1 and members of the HOX family like HOXB13, HOXB7, HOXD4, HOXC10 and HOXC8." (PMID 38201640, 2024).
bile duct cancer (2 papers, 2012 to 2014). "Up-regulated expression of IGF2BP3, NEK2 and HOXB7 mRNA in our study confirms recent reports suggesting detection of tumor-associated gene expression profiles in biliary tract specimens as potentially useful tools in the diagnosis of bile duct cancer." (PMID 22879911, 2012). "In addition, HOXB7 has been suggested as a marker in brush cytology specimens to distinguish bile duct cancer patients from patients with biliary strictures." (PMID 24586698, 2014).
cutaneous squamous cell carcinoma (2 papers, 2021 to 2025). "In the cutaneous squamous cell carcinoma (CSCC) cells, HOXB7 bound to β-catenin, and HOXB7 knockdown reduced cell viability and tumor growth by inhibiting the Wnt/β-catenin signaling pathway." (PMID 33479226, 2021).
metastatic disease (2 papers, 2017 to 2021). "Knockdown of HOXB7 in SMMC-7721 cells inhibited metastasis, and SMMC-7721/scramble cells expressing more HOXB7 formed a conspicuous metastatic tumor in the lung." (PMID 28646927, 2017).
anencephaly (1 paper, 2019). A rare neural tube defect during pregnancy, resulting in the absence of a large portion of the brain and skull in the fetus. "To investigate the potential effect of expression levels of the selected HOX genes (HOXA1, HOXA7, HOXA9, HOXA10, HOXB1, and HOXB7) in anencephaly, we evaluated 10 anencephaly cranial tissues and 10 matched normal fetus cranial samples by the NanoString technique." (PMID 30992047, 2019). "Notably, the expression of HOXA7, HOXA10, and HOXB7 genes was negatively correlated with CUL4B levels in human anencephaly NTD cases." (PMID 30992047, 2019).
astrocytomas (1 paper, 2021). "In conclusion, HOXB7 is a robust diagnostic marker at differentiating between oligodendroglioma and astrocytoma with good sensitivity and specificity." (PMID 34458259, 2021). "Taken together, these results suggest the utility of HOXB7 as a novel marker to differentiate oligodendroglioma from astrocytoma." (PMID 34458259, 2021). "Additionally, HOXB7 is also a highly sensitive and specific indicator to differentiate oligodendroglioma from astrocytoma." (PMID 34458259, 2021). "In this study, we found that HOXB7 may have utility as a novel marker to differentiate oligodendroglioma from astrocytoma." (PMID 34458259, 2021). "In addition, we evaluated the sensitivity and specificity of HOXB7 as a marker to differentiate oligodendrogliomas from astrocytomas." (PMID 34458259, 2021). "Moreover, HOXB7 protein was deleted in 90.9% (20/22) of oligodendrogliomas and 13.0% (3/23) of astrocytomas." (PMID 34458259, 2021). "Finally, to verify the reliability of HOXB7 in differentiating oligodendrogliomas from astrocytomas, we used 1p/19q FISH testing as a positive control." (PMID 34458259, 2021). "It is interesting to find that HOXB7 protein was negative in 20 of 22 cases of oligodendrogliomas (including WHO grade II and grade III) but in 23 cases of astrocytomas (including WHO grade II and grade III), there was a loss of HOXB7 protein expression in only 3 cases." (PMID 34458259, 2021).
atrial fibrillation (1 paper, 2025). A disorder characterized by an electrocardiographic finding of a supraventricular arrhythmia characterized by the replacement of consistent P waves by rapid oscillations or fibrillatory waves that vary in size, shape and timing and are accompanied by an irregular ventricular response. "Similarly, variants near GATA4 and members of the HOXB family of transcription factors such as HOXB7 have been associated with hypertension, while HAND2 variants are associated with aortic dimension and atrial fibrillation." (PMID 40931195, 2025).
bladder cancer (1 paper, 2025). "First, the 5637–T24 cell line model was selected for their contrasting endogenous HOXB7 expression, enabling us to assess both gain- and loss-of-function within a well-established, literature-supported system for bladder cancer." (PMID 41040515, 2025).
Central diabetes insipidus (1 paper, 2024). A form of diabetes insipidus related to a failure of vasopressin (AVP) release from the hypothalamus. "Since QPC deletion is restricted to kidney CD cells, it is unlikely that abnormal central AVP secretion (i.e., central diabetes insipidus) or primary polydipsia are contributing to the urinary concentration defect observed in HoxB7-Qpc–/– mutants." (PMID 39361429, 2024).
chordoma (1 paper, 2021). Chordomas are rare malignant tumors arising from embryonic remnants of the notochord in axial skeleton. "The genes HOXB7, HOXB13, and HOXA-AS3 were detected among the upregulated genes in recurrent chordomas." (PMID 34330313, 2021).
chronic lymphocytic leukemia (1 paper, 2020). "HOXB7 gene in chronic lymphocytic leukemia is hypermethylated and represses Death-Associated Protein Kinase 1 gene expression." (PMID 33225883, 2020).
cutaneous melanoma (1 paper, 2021). A primary melanoma arising from atypical melanocytes in the skin. "There is no past evidence for a role of HOXB7 in UM tumorigenesis, but HOXB7 has been shown to be overexpressed in other cancers, including cutaneous melanoma 80, and could contribute to a pro-proliferative state in the presence of the tumour microenvironment." (PMID 34149931, 2021).
cystic kidney disease (1 paper, 2017). A congenital or acquired kidney disorder characterized by the presence of renal cysts. "Previous work showed that HoxB7-Cre-driven deletion of cilia genes results in severe cystic kidney disease with kidneys becoming ~10 fold larger than normal by P21." (PMID 28410364, 2017).
cystic kidneys (1 paper, 2025). "Notably, levels of Lcn2 transcripts significantly increased in Hoxb7-Cre; Pkd1f/f cystic kidneys compared to Hoxb7-Cre; Pkd1f/f; Ankmy2f/f P3 kidneys." (PMID 41474822, 2025).
depression (1 paper, 2019). "Other studies that investigated DNA methylation signatures of depression in discordant monozygotic twins study design implicated epigenetic changes in VDR26, HOXB7, CACNA1C, STK32C, NR1C3, and MYC genes among others, but not in KLK8 or DAZAP247,108,117,118." (PMID 31477683, 2019).
endometrial cancer (1 paper, 2019). Primary or metastatic malignant neoplasm involving the endometrium (mucous membrane that lines the endometrial cavity). "Six HiChIP target genes (BRAP, RASGRP1, HOXB1, HOXB6, HOXB7 and HOXB8) were enriched for miRNA targets of MIR196A1, itself a HiChIP target gene, providing evidence to link these genes together in a potential network that may mediate the effects of endometrial cancer risk variation." (PMID 31561579, 2019).
esophageal tumors (1 paper, 2022). "Moreover, MAGI2-AS3 delayed the malignant progression of esophageal tumors via transcriptional repressing HOXB7 expression." (PMID 35656441, 2022).
gastric tumor (1 paper, 2017). "To further study the relationship between HOXB7 expression, clinical pathological parameters and prognosis, we first sought to validate the trend of increased HOXB7 expression in gastric tumor tissue." (PMID 27901487, 2017).
hemangioblastoma (1 paper, 2016). "Furthermore, the hemangiomas in HOXB7-Cre driven Vhlh knockouts exhibit extramedullary hematopoiesis that is also observed in human hemangioblastoma but not in liver with hepatocyte Vhlh knockout (either Albumin-Cre or PEPCK-Cre driven)." (PMID 27733136, 2016).
hemangioma (1 paper, 2016). A benign vascular lesion characterized by the formation of capillary-sized or cavernous vascular channels. "Next, both hemangiomas and gross-morphologically healthy looking liver tissue were dissected out of livers of HOXB7-Cre; Vhlhfl/fl mice." (PMID 27733136, 2016). "In HOXB7-Cre driven Vhlh knockout mice, hemangiomas develop with higher penetrance (90 % vs ~40 %) and at a younger age (4–6 weeks versus ~3–8 months) compared to the Albumin-Cre Vhlh knockout mice." (PMID 27733136, 2016). "Interestingly, these HOXB7-Cre; Vhlhfl/fl mice also developed hemangiomas in the liver starting at 3 weeks of age." (PMID 27733136, 2016). "However, despite superficial similarity of the phenotypes, several findings indicate that the mechanism of hemangioma formation is different in hepatocyte-specific Albumin-Cre driven and HOXB7-Cre driven Vhlh knockout mice." (PMID 27733136, 2016). "Furthermore, hemangiomas were partially rescued in HOXB7-Cre; Vhlhfl/fl mice reconstituted with wild-type hematopoietic stem cells." (PMID 27733136, 2016). "Although the hemangioma phenotype recalled the outcome of previous hepatocyte-specific Vhlh knockout mice, to our knowledge, the HOXB7-Cre driver used in our study has not been shown to function in the liver." (PMID 27733136, 2016). "Here, we show that HOXB7-Cre driven Vhlh conditional knockout mice also develop hemangiomas in the liver, although unlike previous models, this Cre driver does not mediate recombination in hepatocytes." (PMID 27733136, 2016). "Interestingly, Vhlh null leukocytes were not sufficient to induce hemangiomas, since no hemangiomas were observed in the reverse experiment (wild-type mice reconstituted with HOXB7-Cre; Vhlhfl/fl hematopoietic stem cells)." (PMID 27733136, 2016).
laryngeal squamous cell carcinoma (1 paper, 2023). A squamous cell carcinoma that arises from the larynx. "Such genes are represented by LC35C1, HOXB7, and TEDC2, and they have the potential to become new therapeutic targets and prognostic biomarkers for laryngeal squamous cell carcinoma." (PMID 36981644, 2023).
leukemia (1 paper, 2015). A malignant (clonal) hematologic disorder, involving hematopoietic stem cells and characterized by the presence of primitive or atypical myeloid or lymphoid cells in the bone marrow and the blood. "We further confirmed that MEIS1 and HOXB7 or MEIS1 and HOXD8 combinations are genuinely synergistic in leukemia induction." (PMID 26606454, 2015). "HOXB7 and HOXD8 are new partners of MEIS1 that have never been reported to have leukemia-inducing potential prior to this study." (PMID 26606454, 2015).
liver hemangioma (1 paper, 2016). A hemangioma arising from the liver. "Here, we report that the same HOXB7-Cre driven Vhlh conditional knockout mice also developed liver hemangiomas as well as extramedullary erythropoiesis." (PMID 27733136, 2016). "Control experiments showed that wild-type donor to wild-type recipient transplantation did not cause any liver phenotype; and that knockout donor to knockout recipient transplantation generated liver hemangioma phenotype with severity indistinguishable from the HOXB7-Cre; Vhlhfl/fl mice." (PMID 27733136, 2016).
metastatic melanoma (1 paper, 2013). A melanoma that has spread from its primary site to another anatomic site. "To test whether these putative BSs were truly functional, we performed a series of promoter luciferase assays by utilizing the highly transfectable 293FT and the metastatic melanoma A375M cell lines, endogenously expressing both HOXB7 and PBX2." (PMID 23400877, 2013).
myelomeningocele (1 paper, 2019). Myelomeningocele is the most severe form of spina bifida. "Our results imply that a methylation change in the body region of PAX3 may be an epigenetic component of human NTDs, which is reminiscent with findings for the HOXB7 gene in a myelomeningocele (spina bifida) case-control study." (PMID 30665459, 2019).
neurofibroma (1 paper, 2024). An intraneural or extraneural neoplasm arising from nerve tissues and neural sheaths. "Therefore, we submitted the six most enlarged dorsal root ganglions for histology and compared them with a para-spinal neurofibroma from the Hoxb7-Cre Nf1f/f, an established neurofibroma model." (PMID 38900740, 2024).
oligodendroglioma (1 paper, 2021). A well-differentiated (WHO grade II), diffusely infiltrating neuroglial tumor, typically located in the cerebral hemispheres. "There may be a point mutation or deletion of HOXB7, which results in the decrease of mRNA level in oligodendroglioma; alternatively the loss of protein expression could be caused by post-translational modification." (PMID 34458259, 2021). "The sensitivity and specificity of HOXB7 protein deletion in oligodendroglioma were 90.9% (20/22) and 87.0% (20/23), respectively." (PMID 34458259, 2021). "To verify the reliability of using HOXB7 in differentiating oligodendroglioma, we used 1p/19q fluorescence in situ hybridization (FISH) testing as a positive control." (PMID 34458259, 2021). "Although two oligodendrogliomas were positive for HOXB7 protein, the number of positive tumor cells and the intensity of positive signal were limited." (PMID 34458259, 2021). "Based on this limited information, we can infer that the diagnosis of oligodendroglioma is more appropriate if the HOXB7 IHC staining of one diffuse glioma was entirely negative." (PMID 34458259, 2021). "We do not know the specific mechanism of HOXB7 involved in the occurrence and development of oligodendroglioma." (PMID 34458259, 2021). "It was surprising to find that HOXB7 protein was completely negative in almost all oligodendrogliomas in our study." (PMID 34458259, 2021). "Furthermore, HOXB7 IHC staining and 1p/19q FISH detection have a high level of concordance in the diagnosis of oligodendroglioma." (PMID 34458259, 2021).
osteoarthritis (1 paper, 2021). A noninflammatory degenerative joint disease occurring chiefly in older persons, characterized by degeneration of the articular cartilage, hypertrophy of bone at the margins and changes in the synovial membrane. "A positive outcome in osteoarthritis treatment has been reported MF-AT had surprisingly higher HOXB7 and bFGF expression in a pathologic SF environment, suggesting that these features are possible players in the beneficial impact on joint homeostasis." (PMID 34454577, 2021).
ovarian tumours (1 paper, 2011). "These treatments could be used alone or in combination with other treatment modalities to increase tumour susceptibility; for example treating ovarian tumours showing highly elevated levels of HOXB7 with HXR9 could sensitise cells to killing by ionising radiation." (PMID 21906307, 2011).
Pleural effusion (1 paper, 2021). The presence of an excessive amount of fluid in the pleural cavity. "Moreover, HOXB7 overexpressing cells showed a colony formation capacity similar to that observed in MCF-7 cells, which is also a line established from a pleural effusion, but without metastatic potential in vivo." (PMID 34063128, 2021).
renal agenesis (1 paper, 2018). Renal agenesis (RA) is a form of renal tract malformation characterized by the complete absence of development of one or both kidneys (unilateral RA or bilateral RA respectively), accompanied by absent ureter(s). "Deleting β-catenin specifically in the UB using homeobox B7(Hoxb7)-Cre led to a range of phenotypes from renal agenesis to cystic/dysplastic kidneys with the severity dependent upon the degree of recombination." (PMID 29364168, 2018).
schwannoma (1 paper, 2020). A benign, usually encapsulated slow growing tumor composed of Schwann cells. "Firstly, complete loss of both Lats1 and Lats2 in the Hoxb7+ lineage resulted in multiple schwannoma formation." (PMID 32960816, 2020). "Hippo pathway inactivation in Hoxb7+ lineage cells results in formation of multiple schwannomas." (PMID 32960816, 2020).